IL2 (interleukin 2)
Diseases named in the same sentence as IL2 in open-access papers (continued):
Sharing a sentence is not in itself a finding about the gene and the disease.
systemic lupus erythematosus (continued). "To confirm these observations also in an in vivo setting, we characterized the IL-2R and IL-7R profiles of T cells from systemic lupus erythematosus (SLE) patients undergoing IL-2 immunotherapy." (PMID 41310351, 2025). "By searching the ClinicalTrials.gov database for the terms “IL-2” and “systemic lupus erythematosus,” we retrieved 18 clinical trials fulfilled our inclusion criteria." (PMID 40337274, 2025). "The search strategy combined MeSH terms and relevant keywords such as ("Systemic Lupus Erythematosus" OR "SLE") AND ("Interleukin-2" OR "IL-2") AND ("low-dose" OR "low dose") AND ("therapy" OR "treatment"), with Boolean operators used to enhance specificity." (PMID 40452697, 2025). "By contrast, the TGF-β producing NK cell we have induced in vivo with CD2 targeted NPs containing IL-2 harvested 5 weeks after NP administration protected lupus mice from renal disease." (PMID 40799646, 2025). "Studies conducted on mice with lupus have demonstrated that administering modest doses of IL-2 can enhance the population of Tregs, decrease disease activity, and enhance survival rates." (PMID 39371877, 2024). "Utilizing low-dose IL-2 treatment has great potential as a novel method to regulate the immune system in patients with systemic lupus erythematosus (SLE)." (PMID 39371877, 2024). "Our results support ongoing efforts to normalize IL-2 in at least a subset of lupus patients, particularly in females." (PMID 38915570, 2024). "Low-dose IL-2 treatment has been demonstrated in clinical studies to successfully enhance the numbers of Treg cells and improve clinical outcomes in patients with systemic lupus erythematosus (SLE)." (PMID 39371877, 2024). "The efficacy and safety of low-dose IL-2 have been confirmed in clinical studies involving rheumatoid arthritis, Primary Sjögren Syndrome, and systemic lupus erythematosus patients." (PMID 38408917, 2024). "Our previous work has shown that the expression of RhoA is significantly higher in lupus T cells and that targeting RhoA can reduce their production of IL-2." (PMID 38243295, 2024). "Low-dose IL-2 therapy increases the circulating Tfr/Tfh ratio, which was accompanied by reduced anti-dsDNA titers and improved kidney damage in mice and lupus patients." (PMID 37771588, 2023). "In vivo, sustained low-dose IL-2 therapy reduced cTfh cells significantly but had little effect on cTfr cells, which resulted in recovered Tfr/Tfh ratio in lupus mice and patients." (PMID 37187757, 2023). "For lupus mice, coculturing UC MSCs with splenocytes upregulated the expression of IL-2 and the proportion of Treg cells." (PMID 38164134, 2023). "Clinical trials with low-dose IL-2 in lupus, given to expand, restore, and improve the function of Tregs, have shown promising results." (PMID 37368057, 2023). "IL-2 is a crucial cytokine involved in T cell survival, activation, and differentiation, and low IL-2 levels were observed in patients with T1D, systemic lupus erythematosus, or rheumatoid arthritis." (PMID 37240014, 2023). "Subcutaneous administration of L72-FSY in murine models of pristane-induced lupus and graft-versus-host disease (GvHD) resulted in enhanced and sustained therapeutic efficacy compared with wild-type IL-2 treatment." (PMID 36690610, 2023). "Diminished interleukin (IL)-2 production is associated with a depleted Treg cell population, and its reversibility by IL-2 therapy provides important reasons for the treatment of lupus." (PMID 37771588, 2023). "When BDF1 lupus-like mice were treated with IL-2-loaded poly lactic-co-glycolic acid nanoparticles (IL-2-loaded NPs) targeted to CD3 T cells, the number of immature CD24+IgM+CD21int/lo transitional 2 cells, mature follicular B cells, and Tfh cells was reduced." (PMID 38164134, 2023).
systemic lupus erythematosus (continued). "To date, much more studies have pointed the role of IL-2 in regulating inflammatory component production either from human beings or from animal models, and recent studies are comprehensively discussing the potential for targeting IL-2 in lupus." (PMID 38164134, 2023). "A randomized cohort study showed that patients with lupus who received prolonged low-dose IL-2 therapy recoveed the immune balance Tfr/Tfh in lupus." (PMID 37771588, 2023). "Recently, efforts have been made to use external IL-2 injection to increase CD4+CD25+CD127low Treg cells in vivo in lupus patients." (PMID 37736101, 2023). "Over the last decade, treatment of patients with systemic lupus erythematosus (SLE) with low-dose interleukin-2 (IL-2) has emerged as a promising new therapeutic modality for the amelioration of disease manifestations without significant side effects." (PMID 37781677, 2023). "In SLE patients and lupus-prone mice, reduced Treg cells were positively correlated with disease activity and impaired T cells’ ability to produce IL-2." (PMID 37474625, 2023). "A randomized, double-blind, placebo-controlled clinical trial was designed to treat active lupus patients who received IL-2 at a dose of 1 million IU or placebo with standard treatment for 3 months and were followed for another 3 months." (PMID 37771588, 2023). "Several explanations have been suggested on this unexpected downregulation of IL-2 in lupus T-cells." (PMID 37215992, 2023). "Costimulation by CD3/CD46 proteins leads to IL-2 dependent Tr1-like cells with high IL-10 and low IFN-γ level production, which is associated with disease activity in lupus patients." (PMID 37771588, 2023). "Collection of the evidence will better understand the roles of the Th1 cell family in lupus pathogenesis, especially targeting IL-2 in lupus." (PMID 38164134, 2023). "Recent two randomized trials have shown that low-dose IL-2 therapy can restore the Treg population in active lupus patients." (PMID 37771588, 2023). "An increased number of Th-17 that promotes neutrophil recruitment and activation and mediates inflammation have also been observed in lupus and it is inversely correlated to IL-2 production." (PMID 36555640, 2022). "Pristane-induced lupus mice showed significantly higher serum levels of IL-1β, IL-2, IL-4, IL-13, IL-21, and IL-22 compared to those in WT mice." (PMID 35911685, 2022). "GDF-15 treatment significantly reduced levels of IL-1β, IL-2, IL-4, IL-21, and IL-22, by which treatment of lupus mice with 100 μg/kg GDF-15 had the most efficiency." (PMID 35911685, 2022). "Enhancing Treg: Teff balance in lupus-prone mice treated with recombinant IL-2 reduced disease progression and increased survival rate." (PMID 36591309, 2022). "In juvenile onset lupus, CREMα has been recognized to drive increased IL-17A expression and reduced IL-2 production in CD4+ T cells." (PMID 35620115, 2022). "So, at the moment, the role of IL-2 as a target for JAK inhibitors is still controversial and more studies are required to clarify the role of IL-2 signalling and its activity in lupus management." (PMID 36015084, 2022). "Alleviation of lupus manifestations was achieved in lupus-prone murine models by reversing the low IL-2 environment." (PMID 35326431, 2022). "For example, administration of IL-2 in patients with systemic lupus erythematosus (SLE) ameliorated disease via the expansion of Tregs without an increased risk of infection, and low dose IL-2 therapy is being investigated in T1D." (PMID 35935980, 2022). "Amongst others, low-dose IL-2 was successfully used in systemic lupus erythematosus and type 1 diabetes mellitus." (PMID 36429085, 2022). "Overproduction of cAMP-responsive element modulator α (CREMα) in total T cells from patients with systemic lupus erythematosus (SLE) can inhibit IL-2 and increase IL-17A." (PMID 36536372, 2022).
systemic lupus erythematosus (continued). "As early as in the 1980s, a long time before the era of Treg, T cells from SLE patients and lupus-prone mice were found to be impaired in their production of IL-2 upon activation." (PMID 33868284, 2021). "Clinical trials of low-dose IL-2 in patients have had selective effects on T regs in healthy individuals, patients with hepatitis C virus-induced vasculitis, type 1 diabetes, and systemic lupus erythematosus." (PMID 34685775, 2021). "Several attempts have been made to compensate for Tac-related immune-dysregulation, including IL-2 replacement, which can lead to flare-ups of lupus-like symptoms, and inhibition of intracellular signals." (PMID 34956169, 2021). "For example, daily administration of low doses interleukin 2 (IL-2) has been linked to expansion of Treg cells and amelioration of graft-vs-host disease as well as induction of remission in systemic lupus erythematosus (SLE) and type I diabetes." (PMID 34539668, 2021). "The downregulation of miR-31 contributed to impaired IL-2 production and signaling in lupus T cells, and the upregulation of miR-21 promoted T cell responses in lupus via targeting PDCD4." (PMID 34062726, 2021). "Lupus is a “low IL-2” disease and this is thought to play a role in the pathogenesis of the disease." (PMID 33748165, 2021). "Interleukin-2 (IL-2) expands the depleted T regulatory (Treg) cell population, and it has emerged as a potential therapy in systemic lupus erythematosus (SLE)." (PMID 33763079, 2021). "We show that the regulatory subunit PPP2R2D is increased in T cells from people with systemic lupus erythematosus and regulates IL-2 production." (PMID 32897879, 2020). "It should be noted that IL-2 and IL-5 were reportedly detected, at the transcriptome level, in keratinocytes from healthy and lupus human skin in the minority of individuals." (PMID 32218380, 2020). "On one hand, low dose IL2 has been proposed as treatment option for certain conditions like graft-versus-host disease, systemic lupus erythematosus and hepatitis C virus-induced vasculitis." (PMID 33110477, 2020). "In mouse models of rheumatoid arthritis and lupus, PR-957 treatment reduces cellular infiltration, autoantibody levels, and cytokine production, including IL-2, IL-6, IL-23, IFN-γ, and TNF-α, effectively alleviating the inflammatory response." (PMID 32595507, 2020). "The efficacy of low-dose IL-2 therapy, which has been shown to restore Treg populations in systemic lupus erythematosus, is currently being evaluated in clinical trials." (PMID 33362780, 2020). "In parallel and in line with previous findings in this lupus model, the frequency of IL-2 producing cells among splenic CD4+CD44hi T cells declined." (PMID 31614462, 2019). "The first report of IL-2 treatment for lupus-prone mice presented in 1990 prior to the discovery of Tregs." (PMID 29755456, 2018). "A recent study reported that decreased miR-200a-3p causes IL-2 hypoproduction in a lupus-prone mouse and that low levels of miR-200a-3p affect the binding of the ZEB1-CtBP2 complex to the IL-2 promoter and suppress IL-2 production." (PMID 29854836, 2018). "Delivery of KN-93 targeted to CD4 T cells to lupus-prone MRL/lpr mice increased IL-2 levels in the serum, reduced IL-17 producing infiltrating cells in the kidneys and improved kidney function as measured by proteinuria." (PMID 30333818, 2018). "In the MRL/lpr lupus-prone mouse, depletion of CaMK4 restores serum levels of IL-2 as well as Treg cell numbers and function." (PMID 30333818, 2018). "In preclinical studies, low dose IL-2 abrogated the development of nephritis in lupus-prone mice and mediated selective expansion of regulatory T cells in SLE patients." (PMID 30524430, 2018). "A recent report showed that SRSF1 enhances IL-2 production in T cells from systemic lupus erythematosus (SLE) patients." (PMID 25658361, 2015). "Despite this hyperactive signaling, lupus T cells fail to produce sufficient amounts of the crucial cytokine IL-2." (PMID 26134847, 2015).
systemic lupus erythematosus (continued). "It is worth noting that lupus T cells are characterized by defective IL-2 expression, enhanced calcium influx, and increased apoptosis, and that lupus is more common in African-Americans compared to European-derived populations." (PMID 26609326, 2015). "In line with our results, it has recently been shown in systemic lupus erythematosus, that cAMP has suppressive activity on IL-2 and IL-7 production through epigenetic modifications in IL-2 and IL-7 promoter genes." (PMID 23658513, 2013). "(2023) highlighted the role of IL-2 in regulating T cells, particularly its function in modulating regulatory T cells (Tregs) to maintain immune homeostasis in autoimmune conditions such as systemic lupus erythematosus and type 1 diabetes." (PMID 40697375, 2025). "Low GAS5 levels were correlated with higher T cell activation status and IL-2 production in lupus." (PMID 41376628, 2025). "Importantly, in a model of murine systemic lupus erythematosus, it was recently shown that low-dose IL-2 directly depletes autoreactive Tfh cells and prevents auto-Ab formation." (PMID 40710339, 2025). "Low‐dose IL‐2 was promising and well‐tolerated in treating systemic lupus erythematosus, which could promote Treg's proliferation and functional recovery." (PMID 38270322, 2024). "Defective IL-2 production is widely reported in both human and murine lupus." (PMID 38915570, 2024). "Conversely, a lupus-prone individual (D2-like) exposed to the same trigger will produce less IL-2 and a weaker Th1 response, with skewing towards a Tfh response that promotes self-reactive B cell maturation and autoantibody production rather than effective downregulation or elimination." (PMID 38915570, 2024). "Similarly, lupus mice treated with IL-2-loaded NPs targeted to Tfh cells showed decreased number of Tfh cells, low serum levels of IgG1 and IgG2a, downregulated proteinuria, and extended survival." (PMID 38164134, 2023). "These were confirmed in other NPs, by which BDF1 lupus-like mice treated with anti-CD2/CD4 antibody-coated NPs encapsulating IL-2 will lead to a higher number of CD4+ and CD8+ Treg cells, decreased expression of anti-dsDNA, proteinuria, and preserved glomeruli." (PMID 38164134, 2023). "As an example, stratifying patients by their IL-2+ Treg titres may dictate response to low-dose IL-2 therapy, as has now been successfully trialled in lupus and RA." (PMID 37215131, 2023). "Similarly, some studies with animal models clarified the role of IL-2 in SLE pathogenesis and blocking lupus development by IL-2 treatment." (PMID 38164134, 2023). "Summary of clinical trials with low-dose IL-2 therapy in systemic lupus erythematosus." (PMID 37771588, 2023). "This review is helpful for better understanding the Th1 family in lupus and may give more clues for targeting the Th1 family including IL-2 in the future in SLE treatment." (PMID 38164134, 2023). "Targeting IL-2 effect on regulatory T (Treg) cells is used in several immune-related diseases, including chronic graft-versus-host disease (cGVHD), type 1 diabetes (T1D), and systemic lupus erythematosus (SLE)." (PMID 35625533, 2022). "Moreover, increased expression of IL-2, IL-21, and IL-22 in lupus mice was downregulated by GDF-15 treatment." (PMID 35911685, 2022). "Moreover, overexpression of GLS2 corrected ROS levels and restored IL-2 production by lupus CD4+ T cells." (PMID 36211442, 2022). "IL-2 and IL-10 depletion and a shift to the Th-1 pathway in the innate response are the correlated mechanism for tumor necrosis factor-alpha inhibitor-induced systemic lupus erythematosus." (PMID 35733860, 2022). "For instance, hsa_circ_0045272 may negatively regulate apoptosis and interleukin-2 secretion in T cells of systemic lupus erythematosus patients." (PMID 35174214, 2022). "In addition, increased soluble form of IL-2R in patients with SLE potentially competes with membrane-bound CD25 for IL-2, rendering lupus T cells less responsive to IL-2." (PMID 35326431, 2022).
systemic lupus erythematosus (continued). "Along with low IL-2 production, hypo-responsiveness to IL-2 in lupus T cells was evident." (PMID 35326431, 2022). "In addition, IL-2 expanded the IL-13-producing lupus CD8+ T cells that also expressed IL-5 and IFN-γ in association with STAT6 phosphorylation and GATA-3 expression, but not with STAT5 phosphorylation." (PMID 33763079, 2021). "Many clinical studies have demonstrated that low-dose IL-2 ranging from 0.3 × 106 to 3.0 × 106 IU improved chronic inflammatory states and outcomes in patients with type 1 diabetes, ischemic heart disease, autoimmune liver disease, and lupus." (PMID 34685775, 2021). "Additionally, abnormal nuclear activity of CamKIV in T cells from patients with lupus leads to binding of CREM to the IL-2 promoter, inhibiting transcription of this gene." (PMID 34403367, 2021). "Another study showed that naïve CD4+ T cells from lupus patients had impaired production of IL-2." (PMID 33271810, 2020). "However, the low PKC levels in summer can still decrease further the low production of IL-2 in T cells of lupus patients augmenting the existing AP-1 defects." (PMID 30715676, 2019). "Indeed, clinical studies have proven that low-dose IL-2 treatment in systemic lupus erythematosus (SLE) patients safely and effectively limits autoimmunity partially through direct inhibition of self-reactive TFH cells." (PMID 31921177, 2019). "Low doses of exogenous IL-2 give Tregs a competitive advantage and increase Treg:Teff ratios, having beneficial effects in preclinical models of multiple sclerosis, autoimmune diabetes, systemic lupus erythematosus (SLE), and graft versus host disease (GvHD)." (PMID 30376867, 2018). "For example, low dose IL-2 has been clinically beneficial in lupus and type I diabetes." (PMID 30150979, 2018). "Our findings demonstrate a critical timing for JES6/IL-2 treatment in the cGvHD model of lupus." (PMID 29670626, 2018). "Calcium calmodulin kinase IV (CaMK4) regulates multiple processes that significantly contribute to the lupus-related pathology by controlling the production of IL-2 and IL-17 by T cells, the proliferation of mesangial cells, and the function and structure of podocytes." (PMID 30333818, 2018). "In particular, low dose IL-2 administration is under active clinical investigation for the therapeutic effects in type 1 diabetes, hepatitis C virus-induced vasculitis, alopecia areata, systemic lupus erythematosus and chronic graft versus host disease." (PMID 26529512, 2015). "The balance between CREB and CREM activity, which is important in determining whether IL-2 is upregulated or downregulated, is altered in lupus T cells." (PMID 24864268, 2014). "In addition, the FoxP3+ Helios+ T cells isolated from 20 lupus patients were shown to have lower IL-2 and IFNγ productions when compared with those from FoxP3+ Helios− T cells." (PMID 24864268, 2014). "In agreement, we have previously shown that hCDR1 inhibited in vitro murine and human T cell proliferation as well as IFN-γ and IL-2 production only in cases of lupus associated responses and did not affect responses to unrelated antigens." (PMID 23555966, 2013). "Production of IL-2 may contribute to the pathogenesis of some diseases: overproduction of IL-2 has been seen in patients with multiple sclerosis, systemic lupus erythematosus relapses, myasthenia gravis and psoriasis." (PMID 16716222, 2006). "Through differential gene enrichment analysis (| logFC | > 1, P < 0.05), our results suggest that LEF1 may influence immune response pathways, including systemic lupus erythematosus, the interleukin-2 signaling pathway, and type II interferon signaling, by regulating associated genes." (PMID 40918098, 2025). "Importantly, our previous studies showing that NPs containing only IL-2 could prevent anti-DNA antibody production in mouse lupus suggested that NK cell-derived TGF-β could eliminate the need to encapsulate this cytokine in the NPs for disease protection." (PMID 40799646, 2025).